FASLG (Fas ligand)
Diseases named in the same sentence as FASLG in open-access papers (continued):
Sharing a sentence is not in itself a finding about the gene and the disease.
tumor (continued). "Alternatively, they can utilize the death receptor pathways of Fas ligand and TNF-related apoptosis-inducing ligand (TRAIL) to kill tumor cells." (PMID 39262781, 2024). "In syngeneic tumor models, expression of FAS DNR in CAR- or TCR-engineered T cells protected the cells from FAS ligand (FASL)-induced apoptosis, leading to improved in vivo persistence and tumor eradication." (PMID 38090585, 2023). "CD8 T-cells can kill tumor cells through various mechanisms, including the secretion of IFN-γ and TNF-α and the expression of death receptor ligands such as the Fas ligand (FasL)." (PMID 37174089, 2023). "Utilizing chemotherapeutic agents like cisplatin, doxorubicin, methotrexate, and etoposide sensitizes tumor cells to NKT cells and affects TRAIL and Fas ligand (FasL) functions in vitro." (PMID 37158883, 2023). "CD8+TILs can exert anti-tumor functions through several pathways such as the release of GZMA and GZMB, Fas-Fas ligand pathway-mediated apoptosis, and secretion of inflammatory cytokines like IFN-γ and TNF-α." (PMID 37781365, 2023). "CNV was positively correlated with the expression of NRGs except FASLG, RIPK3 and TNF in most tumours." (PMID 36583248, 2023). "After activation, NK cells can directly kill transformed cells or tumor cells by producing perforin and granzyme B or by inducing target cell death through tumor necrosis factor (TNF)-α, Fas ligand (FasL), and TNF-related apoptosis-inducing ligand (TRAIL)." (PMID 38022613, 2023). "Some like members of the tumor necrosis factor (TNF)-family like FAS ligand (FASL), TNF and TNF-related apoptosis inducing ligand (TRAIL) can induce tumor-cell apoptosis upon the formation of immune synapses." (PMID 36899361, 2023). "Tumor-derived EVs carrying tumor necrosis factor-related apoptosis-inducing ligand (TRAIL) and Fas ligand (FasL) can induce apoptosis in NK cells and CD8+ T lymphocytes." (PMID 35393416, 2022). "TEXs impaired T cell activity in a tumor microenvironment by reducing the expression of CD3 and JAK3 in primary activated T cells and by mediating Fas/FasL (Fas ligand)-driven CD8+ T cells death." (PMID 36499501, 2022). "Tumor necrosis factor (TNF)-related apoptosis-enhancing ligand (TRAIL), Fas ligand (FasL) and cytokines such as IFN- are involved in tumor cell apoptosis." (PMID 35617812, 2022). "Tumor-derived VEGF and prostaglandin E2 are known to elicit tumor endothelium-dependent killing of CD8+ T cells by expressing Fas ligand (FasL)." (PMID 36011029, 2022). "Among these molecules, Fas ligand (Fas-L) is highly expressed by tumor-infiltrating MDSCs and can induce apoptosis of CD8 cytotoxic T cells by activating Fas-Fas-L axis, with a consequent local immune suppression as demonstrated in mice models." (PMID 35757002, 2022). "Tumor-derived EVs, including TRAIL and Fas ligand, induce the apoptosis of activated anti‐tumor T cells 65-67." (PMID 35265193, 2022). "The regulation network revealed that LINC02195 positively regulates FASLG, which together with FAS initiates cell death and prevents tumor progression." (PMID 36425941, 2022). "FASLG-FAS interaction activated RIPK1 and produce necrosome and finally induced necroptosis in tumor cells." (PMID 35864548, 2022). "The stepwise tumor immunity events are eventually executed through CD8+ T cell‐directed tumor cytolysis, targeting cancer cells by granule exocytosis and Fas ligand (Fas L)‐mediated apoptosis as well as IFN‐γ or TNFα -induced cytotoxicity." (PMID 36059511, 2022). "In particular, six tumor cytotoxicity-related molecules (GZMA, GZMB, GZMH, IFNG, FASLG, and NKG7) from T cells had significantly higher levels in the BM than in PB." (PMID 40977909, 2022). "In complete agreement with our epigenetic profiling data, gene expression of FAS, FASLG, TNFSF10, TRAF1 and TRAF2 was higher in the clusters corresponding to dysfunctional tumor-infiltrating CD8+ T cells." (PMID 35668194, 2022).
tumor (continued). "In our samples, the mRNA levels of CCL5, FASLG, EOMES, and PDCD1 in tumor tissues were significantly higher than those in normal tissues." (PMID 34531849, 2021). "Whiteside and co-Workers affirm that once exposed Treg with tumour Exo, these immunosuppressive cells show enhanced suppressive functions and exhibited a greater expression of IL-10, TGF-β, Fas Ligand, CTLA4, granzyme B (GrB) and perforin." (PMID 34943819, 2021). "Ligands including tumor necrosis factor (TNF), Fas ligand (FasL) and TNF related apoptosis inducing ligand (TRAIL) expressed on exosome surface released by dendritic cells can bind to TNF receptors on tumor cells and trigger caspase activation for apoptosis." (PMID 33892745, 2021). "The overexpression of endothelin B receptor, Fas ligand and VEGF altered the tumor micro-environment, in particularly affecting the tumor endothelial barrier to hinder T-cell homing and infiltration into the tumor." (PMID 33927729, 2021). "NK cell accounts for 50% of the liver lymphocyte population and exhibits anti-tumor function mediated by the release of cytotoxic granules, TNF-related apoptosis-inducing ligand (TRAIL) and Fas ligand (FasL)." (PMID 34067719, 2021). "The tumor necrosis factor (TNF) ligand family members TNFα, Fas ligand (FasL) and Tumor-necrosis-factor related apoptosis ligand (TRAIL) are major immunoregulatory cytokines of the tumor microenvironment, also found to be important SASP components." (PMID 32370259, 2020). "The Lgals9-based network by Cytoscape showed extensive and complex correlation between Lgals9 and other molecules in tumor-immune microenvironment, including CD4, CD19, CD79A, CIS, IL2RG, FCGR2C, and FASLG." (PMID 33082168, 2020). "Under hypoxic conditions, CD8 T cells can differentiate into lytic effector cells, increase the expression of interferon gamma (IFNγ), Fas ligand (FASL), granule B (GZMB), and inhibit tumor cell proliferation 24,25." (PMID 32218698, 2020). "Results of this interaction include upregulated expression of caspases, CD95 (Fas) and secretion of CD95 ligand (Fas ligand), and TNF-related apoptosis-inducing ligand (TRAIL), and enhanced detection of tumor cells by CD8+ and CD4+ T cells." (PMID 32033490, 2020). "TAMs are also known to express Fas ligand (FasL) which acts as an immunosuppressant in GBM, as it contributes to the reduced presence of tumor infiltrating leukocytes." (PMID 32765498, 2020). "Moreover, TZD drugs elicit tumor-suppressive effects to induce apoptosis and inhibit cell proliferation in various cancer cells by regulating apoptosis-associated proteins, such as cyclooxygenase-2 (COX-2), B-cell lymphoma 2 (Bcl-2), epidermal growth factor receptor (EGFR) and Fas ligand (FasL)." (PMID 33266062, 2020). "Second, NK cells express TNF family members such as the TNF-related apoptosis-inducing ligand (TRAIL) and FAS ligand (FASL), which interact with their receptors respectively and elicit tumor cell apoptosis." (PMID 32612950, 2020). "CD4+ T cells can also become directly cytolytic to tumor cells, for example via tumor necrosis factor (TNF)-related apoptosis-inducing ligand (TRAIL) or Fas/Fas ligand (FasL) pathways." (PMID 30956760, 2019). "Do death factors TNF, FasL (Fas ligand) and TRAIL (TNF related apoptosis inducing ligand) play a role in the induction of tumor necroptosis?" (PMID 31922095, 2019). "As well, the expression of members of the tumor necrosis factor (TNF)-family such as FAS ligand (FASL), TNF, and TNF-related apoptosis inducing ligand (TRAIL) induce tumor-cell apoptosis upon formation of immune synapses." (PMID 31035454, 2019). "The de-repression of death receptor transcription by RKIP-promoting drugs (NPI-0052, DETA/NO, etc.), or RKIP overexpression abrogates tumor resistance to TRAIL and Fas-ligand (FasL)-mediated apoptosis." (PMID 30149591, 2018).
tumor (continued). "Some tumor cells express MHC class II, and in such cases, cytotoxic CD4+ T cells have been shown to mediate direct cytotoxic effects via the Fas/Fas ligand or perforin/granzyme pathway." (PMID 30083157, 2018). "The cells function to eradicate the tumor cells by releasing cytotoxic molecules such as TRAIL and Fas ligand, to stimulate DR-induced or extrinsic apoptosis." (PMID 28029652, 2017). "Secondly, γδ T cells upregulate the expression of Fas ligand (Fas-L) and TNF-related apoptosis-inducing ligand (TRAIL) therefore enhance the tumor killing activity in the Fas-or TRAIL-receptor (R) sensitive tumors." (PMID 27823972, 2017). "Most of targets for miR-21 have been identified as tumor suppressors, such as PDCD4 (Programmed cell death 4), PTEN, RECK, TP63 and FASLG." (PMID 29190966, 2017). "These ligands, namely TNF, Fas ligand (FasL), and TNF-related apoptosis-inducing ligand (TRAIL) activate their corresponding receptors present on the tumor cells, inducing apoptotic or necroptotic cell death." (PMID 27843441, 2016). "Supernatants from STAT3-targeted tumor cells increased the expression of NK activation markers, such as CD69, NKG2D, Fas ligand, granzyme B, perforin, and IFN-γ." (PMID 27148255, 2016). "Natural killer T (NKT) cells are a subpopulation of T lymphocytes, which are considered tumor cell killers; they produce antitumor molecules, such as Fas ligand (FasL), IL-4, IFN-γ, IL-13, perforin, and granzyme, that also promote lysis of tumor cells." (PMID 27294132, 2016). "The findings have shown that protein which includes the likes of Eotaxin, Fas ligand, IGF-II, IL-1β, TNF-α, IL-13, Leptin, and TIMP-1 were decreased when compared to the untreated tumor." (PMID 27558166, 2016). "CTLs use various mechanisms to kill tumor cells through granzymes, perforin, and ligands of the tumor necrosis factor (TNF) superfamily such as Fas ligand." (PMID 27686848, 2016). "While the exact mechanism by which C-Fos contributes to tumor suppression is unclear, it is possible that C-Fos mediates apoptosis through the p38 MAP kinase pathway or via induction of Fas ligand as observed in a human T-cell leukaemia cell line." (PMID 25340776, 2014). "S. Typhimurium has been used in several murine trials examining immunotherapies, with significant tumour reduction resulting from local bacterial expression or tumour cell expression of the immune-stimulating molecules IL-18, CCL21, LIGHT or Fas ligand." (PMID 23537317, 2013). "Similar to the MHC class I molecule, Fas (known as CD178 or CD95L) is a key molecule for apoptosis induction of cancer cells through interaction with the Fas ligand secreted by CTLs and the Fas receptor (CD95) on tumor cells." (PMID 23522027, 2013). "The anti-tumor effects of these cells in vivo appears to be, in addition to IFN-g, IL-12, and Fas ligand, dependent on NKG2D as in vivo blockade of NKG2D significantly reduces the anti-tumor efficacy." (PMID 23898464, 2013). "Lenalidomide- and pomalidomide-induced killing correlates with an increase in Fas ligand (FasL) and granzyme B expression in NK cells, leading to increased ADCC in multiple tumor settings." (PMID 22888354, 2012). "Tumors can even directly kill tumor-infiltrating lymphocytes, which are CD95 sensitive, by expressing the CD95L (Fas ligand)." (PMID 22110526, 2011). "On the other hand, cytotoxic CD8+ effector cells play essential roles in the protection against intracellular pathogens and tumor cells by generating IFN-γ, TNF-α, granzymes, perforin, and FAS ligand (FasL)." (PMID 21455314, 2011). "The cytotoxic effects of anticancer immune cells are mediated by perforin/granzyme-B, Fas ligand and tumour necrosis factor-related apoptosis-inducing ligand (TRAIL), and therefore depend on intact apoptotic responses in target tumour cells." (PMID 17311012, 2007).
tumor (continued). "Among the genes involved in the extrinsic route, TRAIL-R1 (DR4) and TRAIL-R2 (DR5) were expressed at the highest level in both low and high MKI tumours, followed by TRAF-1, TRAF-6, Fas and Fas-ligand." (PMID 16755292, 2006). "Second, it renders tumor cells resistant to CD8+ T cells and Fas ligand-mediated lysis." (PMID 40688872, 2025). "TRAIL and FasL expression: Beyond the perforin–granzyme pathway, γδ T cells can also eliminate tumor cells through the expression of TNF-related apoptosis-inducing ligand (TRAIL) and Fas ligand (FasL), which bind to their corresponding receptors on tumor cells to trigger apoptosis." (PMID 40227601, 2025). "A decisive tumor‐suppressive role of FoxOs is present upon cellular damage, which results in FoxO‐mediated induction of pro‐apoptotic genes such as TNFSF10 (TRAIL), FASLG (FasL), BCL2L11 (BIM), or BBC3 (PUMA)." (PMID 39533662, 2025). "For example, low expression of MHC I and MHC II on the surface of tumor cells or expression of immunosuppressive molecules such as vascular endothelial growth factor (VEGF), interleukin-10 (IL-10), Fas ligand (Fas-L), TGF-β and prostaglandin E2 (PGE2) to mediate immune escape." (PMID 38633106, 2024). "Furthermore CAR-T cells upregulate the expressions of Fas ligand (FasL or CD95-L) and tumor necrosis factor-elated apoptosis-inducing ligand (TRAIL) to generate apoptosis-induced cell death in tumor cells." (PMID 39061247, 2024). "Additionally, γδ T cells can target tumor cells by employing mechanisms like engaging death ligands [e.g. TNF-related apoptosis-inducing ligand (TRAIL) and Fas ligand (FasL)] and NK receptors (e.g. NKG2D)." (PMID 38665921, 2024). "CD4 T cells usually do not express Nkg2d; however, a large proportion of tumor-infiltrating NKG2D+ CD4 T cells that release FAS ligands (FASL) are present in patients with tumors." (PMID 39534532, 2024). "Programmed Death-Ligand 1 (PD-L1), Tumor Necrosis Factor (TNF), Fas Ligand (FasL) and TNF-Related Apoptosis-Inducing Ligand (TRAIL) are the main exosomal ligands and their receptors are located on the surface of tumor cells, becoming potential targets for cancer therapies." (PMID 39684236, 2024). "Activated CD8+ T cells directly kill tumor cells by releasing perforin and granzymes and express death ligands, mainly Fas ligand (FasL) and TNF-related apoptosis-inducing ligand (TRAIL), which induce apoptosis of tumor cells through death ligand/death receptor binding." (PMID 39201787, 2024). "Additionally, NK cells can induce cell death via surface molecules such as Fas ligand (FasL) and TNF-related apoptosis-inducing ligand (TRAIL), which bind to their respective receptors on tumor cells, fostering apoptosis." (PMID 39192980, 2024). "To investigate the immune profiles of c-Scorehi tumors across the 25 TCGA tumor types, we evaluated immunomodulatory genes involved in immune checkpoint blockade response, (CD274 [PD-L1], PDCD1 [PD-1], HAVCR2 [TIM3], LAG3, TIGIT, CTLA4, and FASLG)." (PMID 37558751, 2023). "Fas ligand (FasL/CD95L), triggering apoptotic cell death following ligation to Fas (CD95/APO-1), helps to maintain tumor cells in a state of immune privilege by inducing apoptosis of anti-tumor immune effector cells." (PMID 36900418, 2023). "NK cell can also induce tumor killing independent of perforin and granzyme by engagement of Fas Ligand (FasL) and Tumor Necrosis Factor-Related Apoptosis Inducing Ligand (TRAIL) on NK cells with cognate receptors, Fas or TRAIL, expressed on target cells." (PMID 38022679, 2023). "In addition, active angiogenesis of tumor upregulates the suppressive immune molecules, such as PD-L1, IL-6, IL-10, and Fas ligand, which recruit Tregs into TME and clean up cytotoxic T lymphocytes to make it difficult to kill the tumor cells." (PMID 37345194, 2023). "FASLG, TNFRSF1B, GATA3, TARDBP, ZBP1, TNFRSF21, and TLR3 are mainly expressed in multiple immune cell types, and immune cells have a role in TME to inhibit tumor progression." (PMID 35899194, 2022).
tumor (continued). "NK cells lyse tumour cells via granzyme and TNFSF10 and FASLG, secrete cytokines, primarily Th‐1 type cytokines such as IFNG, TNF and granulocyte/ monocyte colony‐stimulating factor (CSF2) which facilitate the activation of T cells and other innate immune mediators." (PMID 35445563, 2022). "Another unique aspect of the aberrant tumour vasculature is the expression of the Fas ligand (FasL), which is absent in normal vasculature." (PMID 36495108, 2022). "In a previous study, LC-MSCs reduced the number of CD4+ T cells producing IL-17 and cytotoxic CD8+ T lymphocytes (CTLs) and suppressed the expression of cytotoxic molecules (Fas ligand (FasL), perforin (PFP) and CD107) in CTLs that mediate anti-tumor immune responses." (PMID 35842634, 2022). "Cytotoxic lymphocytes and NK cells also induce death ligands, (tumor necrosis factor, TNF; Fas ligand, FasL, and TNF-related apoptosis-inducing ligand, TRAIL) to eliminate tumor cells through the activation of their specific receptors present on the tumor cells." (PMID 33807260, 2021). "In hypoxia status, tumor cells inhibited immune cells’ antitumor ability by interacting with inhibitory receptors in immune cells like PDCD1, TIGIT, and LILRB or weakening the immune-stimulation ligand–receptor interactions such as CCL, TNF, and FASLG." (PMID 34956900, 2021). "Additionally, CD8+ T cells can present a membrane-bound protein called Fas ligand (FasL) to the targeted cell, which may be expressing the Fas death receptor, and signalling downstream of the Fas death receptor should then also drive apoptotic pathways within the tumour cell, resulting in its death." (PMID 34295535, 2021). "Due to FASLG/FAS signaling could induce apoptosis commonly in various cancers, the FASLG is summarized as a tumor suppressor." (PMID 34889164, 2021). "TDEVs not only contain the typical exosomal markers, like tetraspanins (CD81, CD63), ESCRT proteins (TSG101), heat shock proteins (HSC70), but also tumor-specific markers such as TAAs (Her2/Neu, Mart1, TRP, GP100), MHC molecules, TNF, Fas Ligand, CD73 or Galectin-9." (PMID 33260499, 2020). "Induction of apoptosis in tumor cells using ligands such as TNF-α, Fas ligand (FasL), TNF–related apoptosis inducing ligands (TRAIL) is an interesting therapeutic approach; however, toxicity and short circulation half-life after systemic administration limits this approach." (PMID 33066447, 2020). "The overexpression of FASLG and PDCD-1 mRNAs in the cell lysates could be related to the tumor immune privilege, as is the case in many other carcinomas." (PMID 33202950, 2020). "Strikingly, this study also shows that certain CAFs may also be able to participate in antigen presentation, leading to direct killing of tumour-reactive CD8+ T cells in an antigen-specific manner through engagement of PD-L2 and Fas ligand." (PMID 32967079, 2020). "However, another study shows that trichostatin A can inhibit apoptosis of tumor infiltrating CD4 T cells by suppressing NFAT1-regulated Fas ligand expression on activated CD4 T cells and thereby enhance anti-tumor immune responses." (PMID 32162275, 2020). "This may suggest that the aberration of FAS in tumours may be yielding the immune-evasion mechanism and that FASLG expression on tumour cells results in the inactivation of killer T cells and hence becoming resistant to FAS–FASLG mediated apoptosis." (PMID 32606315, 2020). "As for T cell related cytotoxins, essential in tumor killing, stacked FPKM of 8 genes (PRF1, GZMM, GZMK, GZMH, GZMB, GZMA, FASLG, and FAS) demonstrated that these genes were more highly expressed 1.7-fold (P = 0.037) in IFNγ positive tumors compared to IFNγ negative tumors." (PMID 32265897, 2020). "We harvested fresh NK cells from non-tumor bearing wild type C57BL/6 mice and treated them with NextA in vitro to investigate the reported markers for NK cell activity and cytotoxicity, such as Granzyme B, TRAIL, and Fas ligand." (PMID 30992475, 2019).